APOO (apolipoprotein O)
Description:
Component of the MICOS complex, a large protein complex of the mitochondrial inner membrane that plays crucial roles in the maintenance of crista junctions, inner membrane architecture, and formation of contact sites to the outer membrane. Plays a crucial role in crista junction formation and mitochondrial function. Can promote cardiac lipotoxicity by enhancing mitochondrial respiration and fatty acid metabolism in cardiac myoblasts. Promotes cholesterol efflux from macrophage cells. Detected in HDL, LDL and VLDL. Secreted by a microsomal triglyceride transfer protein (MTTP)-dependent mechanism, probably as a VLDL-associated protein that is subsequently transferred to HDL.
Synonyms: FAM121B; MIC23; MIC26; My025; MGC4825; MICOS26
Tractability: Antibody: UniProt places it where antibodies can reach, with high confidence; its Gene Ontology location is reachable by antibodies, with high confidence; UniProt predicts a signal peptide or a membrane-spanning region. PROTAC: ubiquitination databases record sites on it; its protein half-life has been measured.
Gene: Protein-coding gene on chromosome X (23,833,353 to 23,908,070, reverse strand). Ensembl gene ENSG00000184831.
Subcellular location: Mitochondrion inner membrane; Secreted; Mitochondrion; Golgi apparatus membrane; Endoplasmic reticulum membrane
Subcellular location (Human Protein Atlas): Mitochondria; Cytosol; Predicted to be secreted
Pathways (Reactome):
Organelle biogenesis and maintenance: Cristae formation
Gene Ontology:
Molecular function: protein binding
Biological process: cristae formation; inner mitochondrial membrane organization
Cellular component: endoplasmic reticulum membrane; extracellular region; Golgi membrane; MIB complex; MICOS complex; mitochondrial inner membrane; mitochondrion; SAM complex; mitochondrial crista junction
Homologues: Orthologues: macaque APOO (99% identical), chimpanzee APOO (94% identical), pig APOO (90% identical), guinea pig Apoo (89% identical), mouse Apoo (83% identical), rat Apoo (80% identical), rat Apool2 (69% identical), tropical clawed frog apoo (46% identical), zebrafish apooa (45% identical), zebrafish apoob (34% identical), Drosophila melanogaster Mic26-27 (26% identical), Caenorhabditis elegans moma-1 (22% identical). Paralogues in human: APOOL (34% identical).
Diseases named in the same sentence as APOO in open-access papers:
APOO is named in the same sentence as 36 diseases in open-access papers, as found by Europe PMC text mining. Sharing a sentence is not in itself a finding about the gene and the disease. The quoted sentences say what the papers report.
lactic acidosis (4 papers, 2020 to 2025). Metabolic acidosis characterized by the accumulation of lactate in the body. "More recently, a mutation in APOO, encoding MIC26, has been reported to cause an X-linked disease associated with developmental delay, hypotonia, autistic spectrum disorder, gastrointestinal symptoms, lactic acidosis and abnormal carnitine profile." (PMID 32858900, 2020).
Mitochondrial myopathy (4 papers, 2020 to 2025). "Mutations in some MICOS components have been reported in humans, including MIC13/QIL1, causing a severe form of infantile hepato-encephalopathy; MIC26/APOO, associated with an X-linked mitochondrial myopathy with cognitive impairment; and MIC60, linked to Parkinsonism." (PMID 36830747, 2023).
atherosclerosis (1 paper, 2025). A disease characterized by the build-up of fatty material and calcium deposition in the arterial wall resulting in partial or complete occlusion of the arterial lumen. "APOO has also been proposed as a metabolic regulator of systemic cholesterol homeostasis and a potential therapeutic target for atherosclerosis management." (PMID 41244589, 2025).
autoimmune thrombocytopenia (1 paper, 2025). An autoimmune form of thrombocytopenia. "Together, these data define APOO as a metabolic-transcriptional checkpoint governing CCR7+CD4+ T cell fate, whose repression fosters dysfunctional differentiation and immune imbalance in autoimmune thrombocytopenia." (PMID 41244589, 2025).
cardiomyopathy (1 paper, 2019). A disease of the heart muscle or myocardium proper. "For example, Turkieh and colleagues showed recently that apolipoprotein O (APOO) is overexpressed in diabetic hearts, and, using transgenic APOO mice, show that APOO links impaired mitochondrial function and the onset of cardiomyopathy." (PMID 31083560, 2019).
Hepatic steatosis (1 paper, 2022). Steatosis is a term used to denote lipid accumulation within hepatocytes. "In the present study, we identified novel targets of miR-200c, Hnf1b, and ApoO, regulating TG secretion and mitochondrial function, providing previously unappreciated mechanisms for alcoholic hepatic steatosis." (PMID 35460694, 2022). "Since both overexpression and knockdown of ApoO impair mitochondrial function, future studies will require to address in more detail how APOO regulates mitochondrial function and contributes to fatty liver disease under certain pathophysiological conditions." (PMID 35460694, 2022).
hepatocellular carcinoma (1 paper, 2013). A malignant tumor that arises from hepatocytes. "The gene expression profile of HepG2 human hepatocellular carcinoma cells transfected with the apoO silencing vector was investigated using a whole-genome oligonucleotide microarray." (PMID 24341743, 2013).
infection (2 papers, 2013 to 2020). The state of being infected such as from the introduction of a foreign agent such as serum, vaccine, antigenic substance or organism. "qRT-PCR and Western blot analysis confirmed that LV2 could significantly inhibit apoO expression in HeLa cells when the multiplicity of infection (MOI) =10 (P < 0.001), whereas LV1 and LV3 had no apparent effect (P > 0.05)." (PMID 24341743, 2013).
cardiovascular disease (1 paper, 2023). "LOC644649 encodes for apolipoprotein O, a protein involved in lipid metabolism and cardiovascular disease, and has been showing sexually dimorphic DNA methylation patterns in cord blood samples." (PMID 37608375, 2023).
heart disease (1 paper, 2015). "Apoo, which encodes apolipoprotein O, has recently been implicated in diabetes-related heart disease." (PMID 26398943, 2015).
tumor (1 paper, 2023). "In the TCGA datasets, BC tumor tissue showed elevated gene expression levels of IMMT, CHCHD6, CHCHD3, APOO, and MICOS10 as compared to normal tissue, while the APOOL level was decreased in tumor tissue as compared to normal tissue." (PMID 36899366, 2023).
APOO also shares sentences with these, for which no sentence is quoted: Cognitive impairment (3 papers); Obesity (3); developmental delay (2); diabetes (2); Parkinson disease (2); progeria (2); alcoholic fatty liver disease (1); autism (1); autistic spectrum disorder (1); congenital cataracts (1); diabetic cardiomyopathy (1); dyslipidemia (1); Hyperglycemia (1); hypothyroidism (1); immune deficiencies (1); Insulin resistance (1); Listeria infection (1); metabolic disease (1); mitochondrial disease (1); Mitochondrial encephalopathy (1); myocardial infarction (1); Parkinsonism (1); schizophrenia (1); X-linked disease (1); X-linked recessive mitochondrial myopathy (1).